SNORD116-17 (small nucleolar RNA, C/D box 116-17)
Synonyms: HBII-85-17
Gene: Small nucleolar RNA gene on chromosome 15 (25,083,588 to 25,083,679, forward strand). Ensembl gene ENSG00000206656.
Gene Ontology:
Biological process: RNA processing
Cellular component: nucleolus
Homologues: Orthologues: chimpanzee SNORD116 (100% identical), macaque SNORD116 (100% identical), guinea pig SNORD116 (90% identical), guinea pig SNORD116 (86% identical). Paralogues in human: SNORD116-19 (100% identical), SNORD116-14 (99% identical), SNORD116-15 (99% identical), SNORD116-18 (99% identical), SNORD116-20 (99% identical), SNORD116-21 (99% identical), SNORD116-22 (99% identical), SNORD116-16 (97% identical), SNORD116-12 (93% identical), SNORD116-23 (93% identical), SNORD116-24 (93% identical), SNORD116-2 (89% identical), and 20 more.